SIRT1 (sirtuin 1)
Diseases named in the same sentence as SIRT1 in open-access papers (continued):
Sharing a sentence is not in itself a finding about the gene and the disease.
Obesity (continued). "In the following sections, we describe the role of SIRT1 in delaying the alterations observed in the kidney during obesity and diabetes." (PMID 35277012, 2022). "In a previous study using an in vitro obesity model, ononin showed anti-adipogenic capacity by upregulating SIRT1 and inhibiting PI3K, PPARγ, and adiponectin." (PMID 35990844, 2022). "Summing up, SIRT1 has a significant impact on energy metabolism, and NF-κB signaling is involved in inflammation, which is critical for obesity and insulin resistance." (PMID 35907080, 2022). "As the stimulation of AMPK increases autophagy activity, this suggests a close relationship between SIRT1 and autophagy in skeletal muscle function and development, consequently improving skeletal function and energy expenditure to protect against obesity." (PMID 35909524, 2022). "RSV has been considered to be the most effective SIRT1 activator and plays multifaceted roles in obesity, diabetes, tumors and aging through allosteric activating of SIRT1." (PMID 36587031, 2022). "This review provides an overview of the crosstalk between SIRT1 and autophagy and their implications in obesity, type-2 diabetes mellitus, diabetic cardiomyopathy, and hepatic steatosis." (PMID 35909524, 2022). "SIRT1 can aid in the prevention of the development of the Mets, obesity, and cardiomyopathy.SIRT3 has been shown to impact dyslipidemia and reperfusion damage positively." (PMID 36361416, 2022). "On the other hand, the high sclerostin levels with low SIRT1 in our cohort of patients with obesity fit with the significant downregulation of osteoblasts’ SIRT1 following mechanical stress." (PMID 35267956, 2022). "The role of SIRT1 in obesity-induced renal damage has begun to be recognized through studies on the molecular mechanisms produced by the currently used pharmacological treatments." (PMID 35277012, 2022). "In line with the increase in FM%, SIRT1 concentrations showed a marked decrease in the group of patients with obesity when compared either to normal weight (p < 0.01) and underweight subjects (p < 0.001)." (PMID 35267956, 2022). "Various molecules have been involved in the pathogenesis of obesity, of which SIRT1 has been an important one." (PMID 34746831, 2021). "The deletion of SIRT1 from POMC neurons results in increased propensity to develop obesity, specifically in female mice under nutrient stress." (PMID 33668705, 2021). "It has been reported that the activation/phosphorylation of AMPK alleviates obesity and its related metabolic syndrome via activating the downstream effector SIRT1." (PMID 34600475, 2021). "Alternate day fasting also increased SIRT1 levels in the liver of diabetic mice and reduced insulin resistance, inflammation, obesity and prolonging of insulin signaling." (PMID 33806509, 2021). "SIRT1 also reduces obesity by suppressing PPARg, which leads to reduced fat deposition in adipocytes." (PMID 34746831, 2021). "In summary, hypothalamic SIRT1 signaling appears to be a key mediator of energy metabolism and the physiological response to obesity." (PMID 33572672, 2021). "Purple maize extract rich in ferulic acid and anthocyans was found to prevent HFD-induced obesity in mouse models by promoting white fat browning and thermogenesis, while reducing inflammation, partly through upregulation of SIRT1 and AMPK." (PMID 33806509, 2021). "Activation of Adenosine 5′-monophosphate-activated protein kinase/Sirtuin1 (AMPK/SIRT1) exerts an effect in alleviating obesity and gut damage." (PMID 34600475, 2021). "The activities of AMPK and SIRT1 are reduced in obesity and type 2 diabetes as a result of energy surplus." (PMID 34987473, 2021).
Obesity (continued). "Our study provides a molecular target that can overexpress SIRT1 protein in the liver, pancreas, and adipose tissues, which can be beneficial in the treatment of diabetes, obesity, longevity, etc." (PMID 34017061, 2021). "Overexpression of SIRT1 is able to rescue obesity-induced insulin resistance in POMC neurons of mice where insulin-resistant nuclear FOXO1 has become constitutive." (PMID 33806509, 2021). "Taken together, alteration in AMPK, SIRT1, and mTOR activity occur in energy surplus states such as obesity and type 2 diabetes to compensate for mitochondrial dysfunction and metabolic disorders." (PMID 34987473, 2021). "Specifically, it has been identified that the ARC is the main integrator area of these effects, with epigenetic inhibition of Kiss1 by SIRT1 as a key mechanism by which nutritional signals and obesity influence puberty of children." (PMID 33572672, 2021). "In the hypothalamus, SIRT1 has been revealed as an attractive target against obesity and type 2 diabetes in both POMC and SF1 neurons." (PMID 34201257, 2021). "Dysregulation of SIRT1 expression or function has significant implications in the development of obesity, diabetes, cancer, cardiac disease, neurodegenerative disease, metabolic dysregulation, etc." (PMID 34017061, 2021). "In the obesity model, SIRT1 induced transcriptional activation of PGC-1α and increased the expression levels of target antioxidant genes, alleviating the damage caused by oxidative stress." (PMID 33994911, 2021). "SIRT1 has important functions in glucose and fat metabolism in several tissues, including the adipose tissue, liver, and pancreas, and it has been reported that pharmacological activation of SIRT1 may attenuate metabolic dysfunction linked with obesity and other metabolic dysfunctions." (PMID 34578872, 2021). "We observed increased expression of miR‐22, decreased expression of Sirt1, and alterations in the expression of adipogenesis‐related genes in a mouse model of obesity and a human hepatocyte cell line." (PMID 33159388, 2021). "Compared with the results in 3.1, the changes of miR‐22 levels and Sirt1 expression in human hepatocytes were much higher than in the obesity mouse model." (PMID 33159388, 2021). "Sirt1 is a key regulator of tissue homoeostasis, and Sirt1 activation is commonly beneficial in many metabolic‐related diseases such as hypertension, obesity and diabetes." (PMID 33523605, 2021). "For instance, miR-377, an important regulator of adipogenesis, has been shown to target the 3’-UTR of SIRT1 mRNA directly, and downregulate its protein abundance, thereby promoting obesity-induced inflammation and IR." (PMID 34068765, 2021). "In mammals, SIRT-1 acts as a regulator of healthspan, protecting against aging and stressful metabolic conditions such as impaired glucose homeostasis, obesity, and cancer." (PMID 33921991, 2021). "Of all sirtuins, most is known about SIRT1: Sirt1 overexpression or pharmacological SIRT1 activation in mice has been shown to prevent metabolic and age-related disease including insulin resistance, obesity and liver steatosis." (PMID 34712151, 2021). "It was found that, in humans, obesity leads to a decrease in the level of Sirt1 in adipose tissue and its level is restored with a decrease in body weight." (PMID 34360859, 2021). "Our study presents a new mechanism for GLP1-RA treatment in obese kidneys: namely, the GLP1-RA exenatide can rescue SIRT1, which can ameliorate obesity-induced mitochondrial dysfunction, the overproduction of ROS and apoptosis." (PMID 34434166, 2021). "Thereafter, the improved gut microbiota alleviated obesity through the fasting-induced adipose factor (Fiaf) and sirtuin-1 (Sirt1) signaling pathway." (PMID 34631766, 2021). "An important location of SIRT1 is in the hypothalamus, where it plays a vital role in regulating energy homeostasis and suppressing metabolic disease such as obesity and type 2 diabetes." (PMID 34690698, 2021).
Obesity (continued). "Contrastingly, overexpression of SIRT1 in the SF1-VHM neurons render mice more resistant to diet induced obesity due to increased energy expenditure and improved insulin sensitivity in skeletal muscle." (PMID 33668705, 2021). "It is also important to highlight the effects of SIRT1 on conditions related to obesity, such as puberty." (PMID 33572672, 2021). "A link between both AMPK and SIRT1 in hypothalamic SF1 neurons with central control of obesity and diabetes has been established." (PMID 34201257, 2021). "There is therefore significant interest in the identification of SIRT1-dependent molecular pathways relevant to adipogenesis and obesity." (PMID 33854178, 2021). "Collectively, these findings show that exenatide was superior to simvastatin in the treatment of obesity-TECs injuries, the mechanism is partially through SIRT1 restoration, which directly reverses mitochondrial dysfunction and apoptosis." (PMID 34434166, 2021). "Downregulation of SIRT1 during obesity—when new adipocytes need to be constantly generated—seems therefore to be expected." (PMID 33806509, 2021). "The AMPK/SIRT1/PGC-1α pathway is an important signaling pathway that mediates the pathophysiological process of IR in obesity." (PMID 33966249, 2021). "In the context of obesity, resveratrol appears to be responsible for modulating mitochondrial activity for which activation of SIRT-1 plays a key role." (PMID 33921991, 2021). "The authors showed the anti-obesity effect of resveratrol treatment through the suppression of lipogenesis and SIRT1 protein expression, attenuation of leptin resistance, and induction of lipolysis for offspring." (PMID 34371900, 2021). "Mediators of obesity-induced endothelial dysfunction include altered endothelial nitric oxide synthase (eNOS), Sirtuin 1 (SIRT1), oxidative stress, autophagy machinery and endoplasmic reticulum (ER) stress." (PMID 32907629, 2020). "Despite this limitation, it can be concluded that adipose tissue SIRT1 play a role in the beneficial effect of BBR on obesity-related disorders from the significant different action of BBR on WT obese mice and Sirt1+/− obese mice." (PMID 33390968, 2020). "Sirtuin 1 (SIRT1), a deacetylase that protects from obesity and regulates metabolism, has been identified as caspase-1 substrate." (PMID 32545788, 2020). "Our data showed that BBR suppressed obesity-induced adipose tissue and systemic inflammation was dependent of SIRT1." (PMID 33390968, 2020). "SIRT1 showed a good predictive strength for FM, particularly in the obesity group, where the best R2 was recorded for EFT (R2 = 0.7)." (PMID 33202604, 2020). "During pathophysiological conditions, such as obesity, SIRT1 expression is altered in the vasculature leading to endothelial dysfunction." (PMID 32907629, 2020). "Wild type (WT) and Sirt1+/− mice were fed either a normal chow (NC) or a HFD to induce obesity for 12 weeks and were then administered different doses of BBR (25 or 50 mg/kg body weight) for 2 weeks." (PMID 33390968, 2020). "In this study, we found that maternal HFD/obesity decreased adiponectin, pAKT, SIRT1, and BDNF in the adult male offspring dorsal hippocampus." (PMID 32408716, 2020). "This miRNA has been shown to be increased during obesity and to induce inflammation in ECs via reduction of SIRT1." (PMID 32907629, 2020). "AMPK and SIRT1 are major enzymes that regulate lipid metabolism, and their activation leads to beneficial effects on metabolic diseases, such as obesity and type 2 diabetes." (PMID 32899992, 2020). "For example, PARP1/2 knockout enhances SIRT1 activity leading to increased mitochondrial function, fatty acid oxidation and protection against obesity." (PMID 32423100, 2020). "Loss of Sirt1 from the liver accelerates the metabolic disturbances of a high-fat diet, while Sirt1 overexpression improves many of the metabolic consequences of obesity and diabetes." (PMID 33036437, 2020).
Obesity (continued). "Levels of SIRT1 have been found to be low in obesity and aging, and normalization of SIRT1 levels decreases disease effects." (PMID 32102680, 2020). "Previous studies have shown that increasing SIRT1 expression or activity can mitigate obesity and related disorders, including adiposity, insulin resistance and hepatic steatosis." (PMID 33027895, 2020). "In this study, we observed that maternal HFD/obesity decreased adiponectin, pAKT, SIRT1, and BDNF in rat fetal brain, and maternal resveratrol treatment was able to restore adiponectin, pAKT, and BDNF in male fetal brain." (PMID 32408716, 2020). "In obese mice, treatment with SRT1720 (a SIRT1 specific activator) prolongs the lifespan and reverses obesity-induced organ damages via normalizing the acetylation of PGC-1α to promote mitochondrial biogenesis in adipose tissue." (PMID 33050331, 2020). "Taken together, these studies suggest a protective role of adipose SIRT1 in maintaining lipid and glucose homeostasis and inflammatory control, which is otherwise abrogated in the development of obesity and T2D." (PMID 33193730, 2020). "We found a parallel but opposite behavior of SIRT1, leptin and adiponectin in patients with obesity." (PMID 33202604, 2020). "Collectively, the data suggest that parental SIRT1 overexpression can ameliorate adverse metabolic programming effects by maternal obesity." (PMID 33027895, 2020). "Since NAD+-dependent SIRT1 activity is essential for a normal metabolic function, treatments that target the cellular NAD+-SIRT1 axis represent a potential preventive/therapeutic intervention strategy for obesity- and aging-related metabolic disorders." (PMID 32143417, 2020). "Our findings indicate that adipose tissue SIRT1 is a major regulator of the therapeutic effects of BBR in obesity-related insulin resistance and metabolic disorders." (PMID 33390968, 2020). "Maternal HFD/obesity decreased adiponectin, phosphorylation alpha serine/threonine-protein kinase (pAKT), sirtuin 1 (SIRT1), and brain-derived neurotrophic factor (BDNF) in rat placenta, male fetal brain, and adult male offspring dorsal hippocampus." (PMID 32408716, 2020). "Treatment with resveratrol, a SIRT1 activator, ameliorates fatty liver with a reduction in the expression of lipogenic enzymes in mice exhibiting obesity and insulin resistance." (PMID 32230804, 2020). "SIRT1 is directly implicated on the levels of SIRT3 whose functions appear reduced in aging and in obesity." (PMID 32335547, 2020). "Among the important factors involved in controlling metabolic disorders and preventing obesity are Sirtuin-1 (SIRT1) and Peroxisome Proliferator-Activated Receptor Gamma Co-activator 1-Alpha (PGC-1α)." (PMID 32586268, 2020). "Ample evidence supports the adipose-specific knockdown of SIRT1 results in obesity, dyslipidemia, and insulin resistance." (PMID 33324265, 2020). "We found that circulating SIRT1 correlates well with visceral fat and has a greater R2 value in predicting FM compared with leptin and adiponectin in patients with obesity." (PMID 33202604, 2020). "HFD and obesity have been shown to significantly reduce the expression of miR-149, thereby lowering SIRT1 activity." (PMID 32907629, 2020). "A study indicated that TGR5 activation inhibited kidney disease in obesity and diabetes by inhibiting oxidative stress via promoting sirtuin 1 (SIRT1) and sirtuin 3 (SIRT3) expression." (PMID 33298860, 2020). "During obesity, miR-204 is highly expressed in ECs, leading to decreased levels of SIRT1 and endothelial dysfunction." (PMID 32907629, 2020). "SIRT1 has a positive impact on metabolic disorders, including obesity, liver steatosis, and diabetes mellitus." (PMID 29803203, 2019). "When overexpressed or activated in mice fed sirtuin-activating compounds (STACs), Sirt1 also prevents obesity, improves energy balance, insulin-sensitivity and glucose tolerance, limits the damaging effects of fatty foods and delays ageing." (PMID 31746335, 2019).
Obesity (continued). "Sirt1-deficient mice had inhibited AMPK activity and increased SREBP-1c expression that triggered hepatic steatosis and obesity." (PMID 31083505, 2019). "It has been demonstrated that NAMPT plays a role in the regulation of NAD/SIRT1 biological activity in obesity and insulin resistance." (PMID 31590397, 2019). "SIRT1-deficient mice lack AMPK activity, but SREBP-1c expression is promoted in mice with induced obesity and hepatic steatosis compared to wild-type HFD-induced obese mice." (PMID 30884843, 2019). "In fact, overexpression of Sirt-1 in mice exposed to a high-fat diet provided protection against hepatic steatosis and obesity." (PMID 31744052, 2019). "Whereas an increase in the expression of the SIRT1 protein was observed in cancer, reductions in the SIRT1 level was more common in other diseases such as Alzheimer's Diseases (AD), Parkinson Disease (PD), obesity, diabetes, and cardiovascular diseases." (PMID 30374331, 2018). "Liver-specific Sirt1 ko mice develop hepatic steatosis when underwent fasting and obesity when fed with HFD in insulin-dependent and independent manners." (PMID 30574122, 2018). "It is possible that mild prolonged hyperinsulinemia observed in obesity has already led to a decrease in AT SIRT1 expression in the obese group and thus our experimental hyperinsulinemia did not promote any additional effect." (PMID 29417372, 2018). "Over a decade ago, it was discovered that resveratrol can reduce diet-induced obesity through SIRT1 activation, generating high expectations as a potential anti-obesity molecule; since then, this effect has been shown in both mice and rats." (PMID 30400297, 2018). "Since the discovery of its actions on SIRT1, many other studies have been carried out to determine the potential of resveratrol in the treatment of obesity." (PMID 30400297, 2018). "Resveratrol (Res), a chemical activator of SIRT1, also exhibited improvement of lipid metabolism in pathologic state, such as obesity, type II diabetes and atherosclerosis." (PMID 30563192, 2018). "SIRT1 protein protects the functions of adipose tissue and liver in several aspects such as glucose homeostasis and fat metabolism against severe obesity." (PMID 30374331, 2018). "Compared with Resveratrol, EA was almost equal to the actuation of expression of Sirt1 and the curative effect of obesity was basically identical." (PMID 30425749, 2018). "In support of this, the hypothalamic SIRT1 expression is induced upon feeding in the standard fed mice, whereas diet-induced obesity abrogated this induction." (PMID 30532738, 2018). "Sirtuin 1 is involved in protection against metabolic disorders and in the prevention of obesity-induced adipose tissue inflammation." (PMID 29968774, 2018). "In this review, we will first summarize how SIRT1 in the brain relates to obesity, type 2 diabetes, and circadian synchronization, and then we discuss the neuroprotective roles of brain SIRT1 in the context of cerebral ischemia and neurodegenerative disorders." (PMID 30532738, 2018). "Our results identify SIRT1-mediated inhibition of Kiss1 as key epigenetic mechanism by which nutritional cues and obesity influence mammalian puberty." (PMID 30305620, 2018). "In particular, for the best-characterized human SIRT1 (hSIRT1) an important role in regulating pathogenesis of diabetes, obesity, cancer, as well as neurodegenerative, cardiovascular, chronic renal and pulmonary diseases is reported." (PMID 30026749, 2018). "But, then again, human studies have shown that SIRT1 is expressed in visceral adipose tissue and reduced by obesity and echocardiographic measurement of epicardial fat can provide a more specific and sensitive measurement of intraabdominal visceral fat." (PMID 30131769, 2018). "miR-34a regulates the development of obesity and age-related diseases via inhibiting SIRT1 expression." (PMID 29681936, 2018).